ACOD1 (aconitate decarboxylase 1)
Diseases named in the same sentence as ACOD1 in open-access papers (continued):
Sharing a sentence is not in itself a finding about the gene and the disease.
infection (continued). "Indeed, infected Acod1−/− mice expressed higher mRNA levels of Il6, IFNγ, Nos2 and Gbp1 than wild‐type controls in the lungs, but also in the spleen, after intratracheal infection." (PMID 36479617, 2023). "Interestingly, the ACOD1-itaconate axis, a key node modulating immunity and metabolism, is activated post infection." (PMID 37256871, 2023). "ACOD1 is a mitochondrial protein, mainly expressed in myeloid cells, and its inducible expression can be used as a marker and regulator of inflammation during various infections." (PMID 35769880, 2022). "Interestingly, the disorder of Acod1-itaconate axis were identified to be the metabolic phenotype in the hippocampus post infection." (PMID 36618398, 2022). "Interestingly, the disorder of Acod1/itaconate axis, a critical node that masters immunity and metabolism, was identified post infection." (PMID 36618398, 2022). "Moreover, we observed that the infection upregulated the protein expression of Acod1 while downregulating Sdha protein expression (P< 0.05)." (PMID 36618398, 2022). "Acod1 deficiency has been associated with a lack of inflammatory control in several models of bacterial and viral infection in mice." (PMID 34525130, 2021). "This difference may be the consequence of the lower induction of Acod1 in response to infection with B. melitensis." (PMID 34525130, 2021). "Acod1 expression has been reported to temper inflammation and prevent immune-related pathology during Mycobacterium tuberculosis and Respiratory Syncytial Virus infections in mice." (PMID 34525130, 2021). "The authors also report that Acod1 deficiency does not affect the multiplication of B. melitensis in BMDMs, which confirms that the in vitro infection of BMDM cannot be used as a predictive model for the infection of alveolar macrophages in vivo." (PMID 34525130, 2021). "Others have shown that during M. tuberculosis infection Acod1 deficiency affects the control of infection in vivo but not in vitro." (PMID 34525130, 2021). "We observed that the Acod1/Irg1 gene, which codes for cis-aconitate decarboxylase 1, is among the genes most overexpressed in response to infection and we demonstrate that Acod1 participates in the direct control of B. melitensis and B. abortus multiplication in AMs." (PMID 34525130, 2021). "However, based on the comparable activity of ITA on NMI and NMII replication in cell‐free culture and in macrophages in vitro, it is reasonable to expect that the ACOD1‐itaconate pathway will play a similar role during infection with virulent C. burnetii NMI in vivo." (PMID 36479617, 2023). "As the NMII load in spleen and liver was not significantly different between the genotypes, we wondered whether ACOD1 was exclusively required for early control of C. burnetii in the lung in a tissue‐specific manner, or whether the route of infection played a role." (PMID 36479617, 2023). "However, since NMII load was comparable in the spleen and livers of Acod1−/− and wild‐type mice after intratracheal infection, these data indicate that ACOD1 exerts an immunoregulatory function in mice following endotoxin challenge or infection with M. tuberculosis." (PMID 36479617, 2023). "We next asked whether ACOD1 was required for control of C. burnetii during infection in vivo." (PMID 36479617, 2023). "In B. bovis-infected animals, transcripts of aconitate decarboxylase 1 (ACOD1), a regulator of immunometabolism in inflammation and infection, were upregulated by 6.4-fold." (PMID 41398915, 2025). "Upon infection, RAB32 interacts with the mitochondrial immunoresponsive gene 1 (IRG1) product aconitate decarboxylase 1 (ACOD1) and facilitates the delivery of itaconic acid to the pathogen-containing vacuole to inhibit bacterial growth." (PMID 38293014, 2024). "RNA-seq showed that the expression of ACOD1 and its downstream genes (HMOX1, TNFAIP3, TAP1, ATF3, and NRF2) was significantly upregulated post infection." (PMID 37256871, 2023).
infection (continued). "Wt and Acod1-/- C57BL/6 mice were infected with 107 CFU of B. abortus and sacrificed 9 days post-infection." (PMID 34525130, 2021). "Two major metabolic genes involved in M1 polarization were significantly upregulated 5 and 24 h post-infection, the PFKFB3 gene, which stimulates glycolysis, and the ACOD1 gene, involved in itaconate production." (PMID 34399615, 2021). "The ACOD1/ITA axis in myeloid cells is induced by stimuli such as LPS and infection." (PMID 40536592, 2025). "Of the clusters that increased during infection, cluster 3 contained subsets of type I IFN-inducible and inflammatory myeloid-related genes that were only modestly reduced by anti-IFNAR treatment, including Acod1, Ifit2, and Retnla." (PMID 40986319, 2025). "Uptake of added isomers into Acod1-/- macrophages was increased after infection for itaconate and mesaconate, but not for citraconate." (PMID 39156902, 2024). "S. anginosus infection exhibited temporal dynamics on ACOD1 expression (upregulation following 6 h post-infection) and Itaconate production (no significant increase in 24 h post-infection)." (PMID 38289109, 2024). "While ITA was hardly detectable (<4 pmol/μg protein) in resting macrophages, NMII infection strongly increased the intracellular ITA levels (ca. 50 pmol/μg protein) in Acod1+/− but not in Acod1−/− macrophages." (PMID 36479617, 2023). "This study shows that C. burnetii infection strongly induces Acod1 expression which turned out to be essential for the control of NMII replication in macrophages in vitro and a key control mechanism in the early phase of infection in vivo." (PMID 36479617, 2023). "Genes such as TNFα, IL10, TLR15, IL8L1 (CXCLi1), IL8L2 (CXCLi2), NOS2, ACOD1 and PTGS2 were upregulated with infection and microbiota, suggesting that macrophages may largely participate in the pro-inflammatory response described in caecal tissues." (PMID 38098020, 2023). "Bacterial burdens of the Acod1-/- mice are unchanged compared to WT two or three weeks post infection, suggesting that the increase in inflammation is not due to increased bacterial burden." (PMID 38157387, 2023). "Indeed, infection with IAV led to brisk transcription of viral HA and host CXCL10 mRNA in a 72 h time course, whereas ACOD1 mRNA levels increased only in a subset of tissue pieces." (PMID 35025971, 2022). "Secondly, aconitate decarboxylase 1 (ACOD1, also known as immune-responsive gene 1 [IRG1]), has attracted much attention as a multifunctional regulator of immunometabolism in inflammation and infection." (PMID 35677353, 2022). "This suggests that Acod1-mediated ICL-dependent inhibition of Brucella multiplication in our murine infection model is not explained by a simple blockage of the glyoxylate shunt or by the toxic accumulation of propionyl-CoA." (PMID 34525130, 2021). "For example, Acod1-/- but not wt C57BL/6 mice intranasally infected with M. tuberculosis succumbed rapidly, and mortality was associated with increased infection, neutrophilia and production of inflammatory cytokines." (PMID 34525130, 2021). "In response to MG, gene expression is up-regulated at the infection site in pathogen-recognition receptors (e.g. TLR1B), signalling molecules and their receptors (such as CXCL12 and IL17R), adaptive cell-surface receptors (CD74) and various other immunomodulators (e.g. ACOD1)." (PMID 38370402, 2024). "Following infection with M. tuberculosis, Acod1−/− mice developed higher bacterial burden and dysregulated neutrophil accumulation in the lung, but no direct effect on intracellular growth was found in Acod1−/− macrophages." (PMID 36479617, 2023). "The lncRNA ACOD1, which is activated by infection with multiple viruses but not by type I IFN stimulation, can bind to and enhance the catalytic activity of the metabolic enzyme glutamic-oxaloacetic transaminase (GOT2), the activity of which is indispensable for viral replication." (PMID 35495674, 2022).
infection (continued). "As expected, infection of A549 cells did not result in induction of ACOD1 mRNA, but transient transfection with an ACOD1-expressing plasmid led to significant ACOD1 mRNA expression, which was accompanied by appearance of substantial concentrations of itaconate." (PMID 35025971, 2022). "Finally, to determine whether Acod1-dependent control of Brucella infection in vivo is acting via bacterial ICL, wt and Acod1-/- C57BL/6 mice were intranasally infected with 107 CFU of wt or ΔaceA B. abortus and sacrificed 9 days post-infection." (PMID 34525130, 2021). "Ectopic synthesis of itaconate in A549 cells, which do not physiologically express ACOD1, reduced infection-driven inflammation, and DI reduced IAV- and IFNγ-induced CXCL10 expression in murine macrophages independent of the presence of endogenous ACOD1." (PMID 35025971, 2022).
tumor (50 papers, 2012 to 2025). "For example, engineered chimeric antigen receptor‐macrophages (CAR‐Ms) deficient in ACOD1 enhance tumor‐killing activity through excessive reactive oxygen species (ROS) production." (PMID 40904700, 2025). "The expression of ACOD1 in tumor-associated macrophages and the resulting production of itaconate and its release in the tumor microenvironment can inhibit T cell anti-tumor immune responses, as indicated by several studies." (PMID 38487538, 2024). "Another up‐regulated gene Acod1 has been shown to play a role in tumor associated macrophage (TAM) metabolic reprogramming." (PMID 38686626, 2024). "Here, cancer cell-intrinsic itaconate biosynthesis by cis-aconitate decarboxylase (ACOD1 or CAD, encoded by immune-responsive gene 1, Irg1) is shown to facilitate tumor immunogenicity and anti-tumor immunity." (PMID 39349845, 2024). "Here, we show that increased tumor-intrinsic cis-aconitate decarboxylase (ACOD1 or CAD, encoded by immune-responsive gene 1, Irg1) expression and itaconate production promote tumor immunogenicity and anti-tumor immune responses." (PMID 39349845, 2024). "have shown that decreased antigen presenting cell features and immune reactivity in TAMs during tumor progression are enhanced in Acod1‐deficient mice." (PMID 38686626, 2024). "Similar findings were reported very recently regarding a reduced tumor growth in Acod1-/- mice, that was associated with a reduced frequency of MDSC but increased T cell accumulation in the tumor microenvironment." (PMID 38487538, 2024). "Specifically, TAMs exhibit decreased immune reactivity along tumour progression that is instead enhanced in Acod1‐deficient mice." (PMID 35838338, 2022). "Itaconate is synthesized from aconitate via immune response gene 1 (IRG1), also known as aconitate decarboxylase (ACOD1), in tumor-associated myeloid cells and uptake of itaconate by CD8+ T cells has been shown to suppress their proliferation and cytolytic activity." (PMID 40235478, 2025). "Notably, we demonstrate that TAMs display decreased antigen‐presenting cell features and immune reactivity along tumour progression, which are enhanced in Acod1/Irg1‐deficient mice." (PMID 35838338, 2022). "Notably, we uncover decreased antigen‐presenting cell features and immune reactivity in TAMs along tumour progression that are instead enhanced in Acod1‐deficient mice." (PMID 35838338, 2022). "In tumor-infiltrating neutrophils (TINs), ACOD1 expression is driven by GM-CSF–JAK/STAT5–C/EBPβ signalling." (PMID 40931345, 2025). "Itaconate levels in the tumor tissues were measured by LC-MS/MS, and the mRNA expression level of Acod1 was detected by PCR." (PMID 40482348, 2025). "Genetic depletion of Acod1 in mice enhanced T cell-mediated anti-tumor immune responses post-radiotherapy and sensitized the subcutaneous xenograft to radiotherapy." (PMID 40482348, 2025). "Inhibiting the expression of ACOD1 in macrophages can significantly enhance the radiosensitivity of cancer cells and promote anti-tumor immune responses mediated by T cells." (PMID 40482348, 2025). "This suggests that the anti-tumor effect of Acod1 knockout in macrophages combined with radiotherapy is partly dependent on CD8+ T cells." (PMID 40482348, 2025). "Further studies have shown that knocking out the ACOD1 gene in macrophages increases the sensitivity of tumor cells to iron death and improves the efficacy of nivolumab or pembrolizumab." (PMID 41226585, 2025). "Engineered macrophage adoptive therapies, such as CAR‐M cells with ACOD1 deletion, exploit metabolic rewiring to increase ROS production and enhance tumor‐killing activity." (PMID 40904700, 2025). "Experimental evidence showed that the ablation of Acod1 not only decreased TIN density but also significantly inhibited breast cancer metastasis while enhancing the anti-tumor T cell immune response." (PMID 40342932, 2025).
tumor (continued). "We then blocked itaconate generation in combination with doxorubicin treatment using the Acod1-/- EL4 tumor mice model." (PMID 38555305, 2024). "Acod1 ablation in neutrophils resulted in ferroptosis and thus decreased metastases and increased anti-tumor immunity and immune checkpoint blockade efficacy." (PMID 39188677, 2024). "Tumor-infiltrating neutrophils upregulate Acod1 expression to produce itaconate, which mediates Nrf2-dependent resistance to ferroptosis for neutrophil survival, which in turn can drive metastasis." (PMID 39188677, 2024). "Another study reported that aconitate decarboxylase 1 ablation abates Tumor-infiltrating neutrophils infiltration, constrains metastasis, and bolsters antitumor T cell immunity." (PMID 38962561, 2024). "This confirms the recent study demonstrating decreased apoptosis and increased neutrophil supported tumor viability due to the action of Acod1 and itaconate generation." (PMID 38555305, 2024). "In tumor‐infiltrating neutrophils (TINs), ACOD1 is the most significantly upregulated metabolic enzyme." (PMID 39492834, 2024). "Itaconate is a key metabolic component of the crosstalk between tumor and TAM, and TAM can promote tumor progression through ACOD1–itaconate." (PMID 39492834, 2024). "Next, flow cytometry results support the stronger phagocytosis function of ACOD1-/- iMACs against tumor cells." (PMID 37723178, 2023). "Compared with other groups, the combination of the low-dose anti-PD1 antibody with ACOD1-/- MSLN-CAR-iMACs had the most superior tumor suppression effect, and markedly lengthened the survival time." (PMID 37723178, 2023). "Compared with the untreated or the MSLN-CAR-iMACs treated mice, treatment with ACOD1-/- MSLN-CAR-iMACs led to significant inhibition of tumor growth." (PMID 37723178, 2023). "Together, these data strongly demonstrated that ACOD1-deleted CAR-iMACs combined with ICIs had the most superior anti-tumor activity." (PMID 37723178, 2023). "To examine the function of ROS in tumor killing ability of ACOD1-/- MSLN-CAR-iMACs, we added the anti-oxidant reagent N-Acetyl-L-cysteine (NAC) to eliminate ROS in the tumor-iMAC co-culture system." (PMID 37723178, 2023). "Here authors introduce pluripotent stem cell-derived CAR-macrophage that are depleted of ACOD1, an essential gene in itaconate metabolism, which reprograms them to a pro-inflammatory state enabling enhanced anti-tumour function." (PMID 37723178, 2023). "To evaluate the anti-tumor activity of ACOD1-/- MSLN-CAR-iMACs in vivo, we used two different xenograft solid tumor models with the NOD/SCID/IL2rγnull (NSG) mice." (PMID 37723178, 2023). "Overall, our current data support a multi-level mechanism of CAR-iMACs in tumor killing activity, including enhanced direct phagocytosis and more ROS produced by ACOD1 knockout." (PMID 37723178, 2023). "Using a lentivirus to delete the Acod1 gene and thus abolish the conversion of succinate into itaconate in tissue-resident macrophages significantly decreased the tumor volume compared with the control lentivirus group in tumor-bearing mice." (PMID 32724492, 2020). "Consequently, ACOD1 deficiency in TANs promotes their survival within the TME, contributes to tumor-associated immunosuppression, and ultimately diminishes the therapeutic efficacy of ICB." (PMID 40342932, 2025). "Notably, specifically knocking out Acod1 on myeloid cells enhances the activation of the tumor immune microenvironment in response to radiotherapy, particularly increasing the infiltration and activation of CD8+ T cells." (PMID 40482348, 2025). "Additionally, the mRNA expression level of Acod1 in tumor tissues was detected by PCR, and the results were consistent with itaconate." (PMID 40482348, 2025). "High expression of ACOD1 is reported in neutrophils in infection and tumor models." (PMID 40931345, 2025). "Furthermore, to exclude the effect of Acod1 knockout on immune cells, we established a subcutaneous H1299 tumor model using BALB/c-nude mice." (PMID 40482348, 2025).